WDR12 (WD repeat domain 12)
Diseases named in the same sentence as WDR12 in open-access papers (continued):
Sharing a sentence is not in itself a finding about the gene and the disease.
tumor (4 papers, 2020 to 2022). "We retrieved the top 50 interacting proteins and the top 100 linked proteins to WDR12 in tumor tissue from the STRING and GEPIA2 databases, respectively, and found that DKC1 is a promising candidate." (PMID 36726716, 2022). "An essential hallmark of oncogenic proteins is their overexpression in tumor tissue compared to normal tissue; as a result, we evaluated the expression of WDR12 in various malignancies using the TCGA, GTEx, and CPTAC databases." (PMID 36726716, 2022). "The co-expression of WDR12, immune-related genes, and tumor-infiltrating lymphocytes (TILs) was investigated." (PMID 36726716, 2022). "GEPIA2’s “Pathological Stage Plot” module investigated the relationship between WDR12 expression and tumor pathology stages." (PMID 36726716, 2022). "We analyzed WDR12 genetic alterations in multiple tumor samples from the TCGA database using the cBioPortal website." (PMID 36726716, 2022). "The results showed that inducible knockdown of WDR12 inhibited GSC derived tumor growth, as shown by bioluminescent imaging (bottom), and significantly prolonged animal survival." (PMID 34868955, 2021). "To better address the clinical relevance of WDR12, we performed an IB analysis with fresh GBM specimens and confirmed the elevated expression of WDR12 in tumor tissues relative to normal brain tissues adjacent to tumors." (PMID 34868955, 2021). "In human GBM specimens, expression of WDR12 was increased in Ki67+ tumor cells, thus suggesting a correlation of WDR12 levels with tumor cell proliferation." (PMID 34868955, 2021). "While we present evidence that downregulating WDR12 suppresses tumor growth in GBM mouse model, a fraction of GSCs are still remained in the tumors." (PMID 34868955, 2021). "Thus, we examined the relationship between WDR12 expression and tumor-infiltrating immune cells, such as CAFs and MDSCs." (PMID 36726716, 2022). "Combining WDR12 expression data, MDSC infiltration, and CAF infiltration, we may conclude that upregulation of WDR12 may serve as a biomarker for an inadequate immune response against a developing tumor." (PMID 36726716, 2022). "Moving to the tumors that had a small “normal tissue” sample size in the TIMER2 web server, all of the analyzed tumors showed a trend of WDR12 elevated expression in tumor versus normal samples, and this elevation was significant in tumors CHOL, GBM, READ, and PAAD." (PMID 36726716, 2022). "In all tumor types investigated except for UVM, THCA, PCPG, KIRC, DLBC, BRCA-LumB, and BRCA-Her2, the current investigation revealed statistically significant and positively correlated associations between WDR12 expression and MDSCs infiltration." (PMID 36726716, 2022). "Additionally, we found that WDR12 was upregulated in the primary tumor cells isolated from GBM patients, as well as in GSCs, compared to that in the human neural progenitor cells including hNP1 and 16157, and normal human astrocyte (NHA)." (PMID 34868955, 2021). "The results showed that expression of WDR12 was strongly increased in tumor cells expressing SOX2." (PMID 34868955, 2021). "In addition, we observed that silencing WDR12 in tumors remarkably decreased tumor cell proliferation and GSC population, as assessed by Ki67 and SOX2 staining respectively." (PMID 34868955, 2021). "Moreover, depletion of WDR12 strongly inhibited GSC tumor-sphere formation, thus indicating that WDR12 might be required for GSC maintenance." (PMID 34868955, 2021). "Additional studies using CRISPR-Cas9 system to completely knockout WDR12 in vivo will be crucial to establishing the role of WDR12 in GSC maintenance in vivo and in GSC-derived tumor propagation." (PMID 34868955, 2021). "Subsequently, WDR12 depletion compromises GSC proliferation, inhibits GSC-derived orthotopic tumor growth, and extends animal survival." (PMID 34868955, 2021).
tumor (continued). "To explore the effect of WDR12 in vivo, we employed a doxycycline (Dox)-inducible shRNA system to silence WDR12 expression and evaluated its role in GSC-derived tumor growth." (PMID 34868955, 2021). "From the tumor list that lacks a normal sample for comparison on the TIMER2 web server, DLBC, LGG, SKCM, TGCT, THYM, and UCS experienced a significant upregulation in WDR12 in comparison to normal tissue." (PMID 36726716, 2022). "Moreover, WDR12 depletion compromised GSC proliferation, inhibited GSC-derived orthotopic tumor growth, and extended animal survival." (PMID 36726716, 2022). "Together, these data suggest that WDR12 is required for GSC proliferation and GBM tumor growth." (PMID 34868955, 2021). "In this study, we found that WDR12 was preferentially expressed in GSCs relative to non-stem tumor cells (NSTCs) and normal brain cells." (PMID 34868955, 2021). "BAG2 might favor cell proliferation, repress apoptosis and facilitate tumor invasion in HCC, probably through regulation on ribosome biogenesis via genes like WDR12, BYSL, and DCAF13." (PMID 34257542, 2021). "Importantly, depletion of WDR12 decreases the processing of 32S rRNA and the subsequent maturation of 28S rRNA in GSCs, thereby inhibiting GSC proliferation and tumor growth." (PMID 34868955, 2021). "Targeting WDR12 may be a promising therapeutic opportunity to compromise ribosome function and inhibit GSC derived tumor progression." (PMID 34868955, 2021). "Importantly, depletion of WDR12 significantly suppressed GSC proliferation and tumor progression." (PMID 34868955, 2021). "WDR12 is preferentially expressed in GSCs compared to non-stem tumor cells and normal brain cells." (PMID 34868955, 2021).
infection (2 papers, 2022 to 2025). The state of being infected such as from the introduction of a foreign agent such as serum, vaccine, antigenic substance or organism. "Specifically, SNRNP40 and SNRNP70 retained the appearance of nuclear speckles following infection, while WDR12 retained a diffuse nuclear distribution." (PMID 40577456, 2025). "In contrast, almost 100 transcripts related to genes typically involved in viral protein translation during infection (e.g. rps2, 12, 14; wdr12; rpf2; nip7; eif4; eif4ebp3l; eif4a3; eif4ea; eif4b) were down-regulated." (PMID 35710351, 2022).
WDR12 also shares sentences with these, for which no sentence is quoted: breast carcinoma (2 papers); angina pectoris (1); autism spectrum disorder (1); brain tumors (1); colon cancer (1); epithelial ovarian cancer (1); esophageal cancer (1); gastric cancer (1); heart disease (1); ischemic stroke (1); liver cancer (1); lung adenocarcinoma (1); major depressive disorder (1); melanoma (1); oligodendroglioma (1); schizophrenia (1).